EGFR (epidermal growth factor receptor)
Diseases named in the same sentence as EGFR in open-access papers (continued):
Sharing a sentence is not in itself a finding about the gene and the disease.
lung cancer (continued). "EGFR, a tyrosine kinase receptor, is highly expressed in many cancers, such as glioblastoma, colorectal cancer, and lung cancer." (PMID 34552618, 2021). "The univariant analysis showed better PFS in patients that had first-line afatinib in EGFR-mutant lung cancer patients with synchronous BM." (PMID 34577890, 2021). "Here, we showed that SRBEP-1 is a key feature of acquired resistance to gefitinib in EGFR mutant lung cancer and that inhibition of SREBP-1 can overcome gefitinib-acquired resistance." (PMID 34775471, 2021). "Mutations in epidermal growth factor receptor (EGFR) occur in approximately 20% cases of lung cancer, and epidermal growth factor receptor-tyrosine kinase inhibitors (EGFR-TKIs) are indispensable in the treatment of EGFR-mutant advanced LUAD." (PMID 33628780, 2021). "Otherwise, there were 28 mechanically ventilated EGFR wild type lung cancer patients who also received EGFR TKI in ICU during our study period." (PMID 34680533, 2021). "Clinical analysis revealed a significantly higher miR-146b-5p expression in pleural effusions-isolated lung cancer cells from treatment-naive patients than acquiring resistance patients to EGFR-TKI treatment." (PMID 34830377, 2021). "Because EGFR signaling is suppressed in the three acquired-resistance lung cancer cell lines (HCC827 GR, H1993 ER, and H292 ER), we examined glucose metabolism in these cancer cells." (PMID 34367462, 2021). "Our search criteria included the following terms: “drug tolerance” or “drug tolerant”, “lung cancer,” and “EGFR”." (PMID 34202566, 2021). "The approval of the anti-EGFR mAbs—cetuximab and panitumumab—for the treatment of mCRC and, in recent years, necitumumab for lung cancer, emphasises the importance of EGFR as a therapeutic target in human cancers." (PMID 33562755, 2021). "The progress of the landscape of EGFR TKI therapeutics in lung cancer from early generation to osimertinib and beyond reflects the depth of knowledge achieved in the last decade." (PMID 34202748, 2021). "Due to mutations in EGFR and KRAS appearing to be mutually exclusive in lung cancer patients, the results are especially worth noticing." (PMID 33725808, 2021). "In the study, we demonstrated that cinobufagin exhibited specific antiproliferation effect in the special carcinoma cells with EGFR expression, including glioblastoma cells, lung cancer cells, colorectal cells, and hepatocellular carcinoma cells." (PMID 34925034, 2021). "Together, this study suggests a dependence for survival on GPCRs and YAP signaling in EGFR mutant lung cancer." (PMID 34944063, 2021). "Acquired EGFR-TKI-resistant lung cancer cell lines (HCC827, H1993, and H292 cells with acquired resistance to gefitinib or erlotinib) were used for cell-based studies." (PMID 34367462, 2021). "A previous study also reported that plasma exosomal miR-320d is upregulated in progressive disease compared with the partial response of immunotherapy in EGFR/ALK wild-type advanced nonsmall cell lung cancer." (PMID 34503068, 2021). "According to Sacher and colleagues (2016), an application of ddPCR in plasma of individuals with lung cancer appeared to have a positive predictive value of 100% for EGFR 19 del and 100% for KRAS." (PMID 34571783, 2021). "Genetic alterations of NSP3 (SH2D3C) co-occurred inversely with Epidermal Growth Factor Receptor (EGFR) alterations and elicited its pathological role via modulation of various components of the immune and inflammatory pathways in lung cancer." (PMID 34829812, 2021). "The EGFR targeting of osimertinib deprives lung cancer cells of pro-survival signaling, and ROS are known to be generated during pro-apoptotic processes and autophagy." (PMID 34952897, 2021).
lung cancer (continued). "EGFR-mutant lung cancer cells injected into murine CSF via the cisterna magna have been shown to be more sensitive to osimertinib when compared to earlier generation EGFR inhibitors, supporting clinical findings." (PMID 33578853, 2021). "Previously, we also reported that maintenance of EGFR levels and activity is critical for escaping anoikis in A549 lung cancer cells." (PMID 33440835, 2021). "With the input of Cluster 1 cytokines, we revealed a distinct cluster of lung cancer samples with the reduced expression of EGFR and CD274." (PMID 34045585, 2021). "In particular, substituted 4,6-diaminopyrimidines are capable of blocking epidermal growth factor receptor (EGFR), what make them perspective for the lung cancer treatment." (PMID 33805408, 2021). "A model of EGFR‐driven lung cancer and a method to develop tumors of distinct epigenetic states through 3D organotypic cultures are described here." (PMID 34622577, 2021). "EGFR-activating mutations have been correlated with overexpression of PD-L1 in preclinical EGFR-driven lung cancer models, linking EGFR signaling with immune evasion." (PMID 34065396, 2021). "Osimertinib is a third generation tyrosine kinase inhibitor (TKI) that targets the epidermal growth factor receptor (EGFR) in lung cancer." (PMID 33971844, 2021). "For example, EGFR is present in 80% of exosomes purified from the lung cancer biopsies whereas in only 2% of exosomes from patients with chronic lung inflammation." (PMID 34503141, 2021). "For a therapeutic approach to paclitaxel-resistant lung cancer, the EGFR inhibitor gefitinib and the PLK1 inhibitor volasertib or genistein were applied as a single reagent or combinatory reagents in parental and paclitaxel-resistant LUAD." (PMID 34503223, 2021). "Researchers have reported that hsa-miR-30d-3p was down-regulated in lung cancer and its down-regulation promoted tolerance to EGFR-targeted drug in lung cancer patients." (PMID 33842535, 2021). "To first assess the relationship between EGFR status and NE marker expression in lung cancer, we performed western blot analysis across a diverse panel of lung cancer cell lines." (PMID 34121659, 2021). "In fact, in cancers harboring driver oncogenes, such as mutant EGFR in lung cancer and mutant BRAF in melanoma, studies have demonstrated that knockdown or knockout of the oncogene induces robust apoptosis." (PMID 34680229, 2021). "Compared with traditional treatment, molecule-targeted drugs represented by EGFR-TKI have significantly improved the prognosis of patients with advanced lung cancer." (PMID 34367993, 2021). "EGFR expression on pleural endothelial cells provided a potential pathway that can be targeted to control the progression of lung cancer complicated with MAPF." (PMID 34680445, 2021). "Our results propose that LncRNA/SOX2‐OT can disrupt lung cancer therapy resistance capacity, by downregulation of the EGFR‐AKT‐ERK expression and activation rate." (PMID 33433063, 2021). "The use of osimertinib to target epidermal growth factor receptor (EGFR) has become the standard of care in untreated EGFR-mutant non–small cell lung cancer (NSCLC) patients." (PMID 33580193, 2021). "Plasma exosome EGFR expression levels are remarkably different between lung cancer patients and normal controls." (PMID 33504342, 2021). "Despite the limitations of our study as a single-center study of an unselected EGFR mutant lung cancer cohort, this consistent proportion of MET amplification as determinant of resistance makes it reasonable to find the enriched population to evaluate." (PMID 34205733, 2021). "This study compared the feasibility, sensitivity, and specificity of detecting EGFR mutation using BWF, bronchoscopy biopsy, and plasma samples in patients with lung cancer (LC)." (PMID 33828971, 2021).
lung cancer (continued). "Double conjugation with CD133 and EGFR aptamers promoted the entry of the Sali-loaded nanoparticles in H460 and A549 lung cancer cells and CSCs, achieving superior antitumor efficacy both in vitro and in vivo in tumor-bearing mice, compared to controls." (PMID 34452081, 2021). "In lung cancer, for example, a study of 5,688 patients with non–small-cell lung cancer from 2011 to 2016 demonstrated that 15.4% received broad-based genomic sequencing and 84.6% received single gene testing for EGFR and/or ALK." (PMID 34651094, 2021). "Though the case number is small, our study is the largest cohort of EGFR mutant lung cancer patients admitted to ICU with ventilator support." (PMID 34680533, 2021). "Surprisingly, while EGFR inhibition was capable of inducing interferon responses in both EGFR-mutant and wild-type lung cancers, this was NF-κB-independent in EGFR-mutant models but NF-κB-dependent in EGFR wild-type models." (PMID 34071428, 2021). "In vitro studies in A549 lung cancer cell lines have shown that FUT7 overexpression augments sLeX synthesis to trigger cell proliferation via the activation of the EGFR/AKT/mTOR signaling pathway." (PMID 33963380, 2021). "Beyond this preliminary observation, the results of a series of phase II trials are available in the neoadjuvant setting of EGFR mutant lung cancer." (PMID 34685665, 2021). "Epidermal growth factor receptor (EGFR) is one of the anticancer drug targets for certain malignancies including nonsmall cell lung cancer (NSCLC), colorectal cancer (CRC), and head and neck squamous cell carcinoma." (PMID 33801379, 2021). "Recently, molecular therapeutics targeting receptor tyrosine kinase (RTK) aberrations in lung cancer, including epidermal growth factor receptor (EGFR) and anaplastic lymphoma kinase (ALK), and immunotherapies have been developed." (PMID 33826244, 2021). "To understand the expression of PLK1 and EGFR in chemoresistant lung cancer, we analyzed a published transcriptome of gemcitabine-resistant Calu3 lung adenocarcinoma cells (GSE 6914)." (PMID 34503223, 2021). "We found that prednisone is significantly more effective compared to etanercept in blocking the adaptive transcriptional response to EGFR inhibition in lung cancer cells, while thalidomide has an intermediate effect." (PMID 34853306, 2021). "This provided a potential combination therapeutic strategy for the treatment of EGFR-TKI resistance lung cancer." (PMID 33391507, 2021). "Our clinical results showed for the first time a noteworthy positive correlation between YAP and p62 in EGFR‐mutant lung cancer patients’ tissues." (PMID 33486901, 2021). "Taken together, our findings suggest that nuclear PKM2 translocation contributes, in part, to PSAT1-mediated cell migration under EGFR activation in lung cancer." (PMID 34439090, 2021). "We applied the developed CNN to an external clinical CT data of lung cancer patients with known EGFR status." (PMID 34941646, 2021). "We conclude that our new mouse strain mimics the osimertinib resistance observed in patients with EGFR-mutated and MET-amplified lung cancer." (PMID 34298655, 2021). "Taken together, we propose the potential use of SB as a novel therapeutic for lung cancer patients with EGFR TKI resistance." (PMID 34068421, 2021). "For example, MET activation, by either gene amplification or ligand stimulation, accounts for 5–10% of lung cancer resistance to EGFR TKIs." (PMID 34071428, 2021). "The resultant products from some activated proto-oncogenes (c-sis and c-erbB-2) are the homologous sequences to some specific growth factor (such as platelet-derived growth factor (PDGF)) and the EGFR, commonly identified in lung cancer." (PMID 35008242, 2021).
lung cancer (continued). "Emerging studies have documented that afatinib, a novel and irreversible pan-EGFR inhibitor, effectively induces autophagy in lung cancer cells." (PMID 34294686, 2021). "Although we demonstrated that irradiation significantly suppressed the cell viability in the EGFR-positive lung cancer cell lines, a previous literature has demonstrated that repeated irradiation exposure induces EGFR expression and activation." (PMID 34685495, 2021). "The treatment mode of lung cancer is epidermal growth factor receptor-tyrosine kinase inhibitors (EGFR-TKIs) as a first-line treatment for patients with EGFR mutant in non-small cell lung cancer (NSCLC)." (PMID 34455737, 2021). "Another tyrosine kinase inhibitor, gefitinib, an epidermal growth factor receptor (EGFR) inhibitor, is used for breast and lung cancers." (PMID 34745105, 2021). "The discovery of EGFR tyrosine kinase inhibitors (TKI) for the treatment of EGFRm metastatic NSCLC was regarded as a landmark in lung cancer." (PMID 34940073, 2021). "Previous preclinical and clinical studies with HSP90i have demonstrated activity in EGFR-mutant non–small cell lung cancer (NSCLC)." (PMID 34140248, 2021). "In the past decade, two important sources of mutations in lung cancer have been discovered, namely Kirsten RAt Sarcoma 2 viral oncogene homolog (KRAS) and epidermal growth factor receptor (EGFR) mutations." (PMID 32530390, 2021). "This cohort study assesses characteristics and recurrence patterns of resected early-stage epidermal growth factor receptor (EGFR)–positive non–small cell lung cancer." (PMID 34739062, 2021). "In the past 10 years, tyrosine kinase inhibitors (TKIs) for epidermal growth factor receptor (EGFR) have demonstrated remarkable clinical effects and paved the way for effective treatment of lung cancer." (PMID 34217313, 2021). "Taken together, these data further support a role of CIP2A in the response of lung cancer cells to EGFR tyrosine kinase inhibitors." (PMID 33804833, 2021). "Recently, WWP1 was discovered to bind with EGFR and increase its ubiquitination and enhance EGFR stability, resulting in enhanced lung cancer progression." (PMID 34226507, 2021). "Our results suggest that SLB procedures (such as VATS lung biopsy) should be the procedure of choice for obtaining tissue samples for diagnosis, subtyping, and EGFR analysis in patients with a lung lesion in whom lung cancer is suspected." (PMID 33425564, 2021). "Granzyme B was considered a hydrolase enzyme leading to tumor cell apoptosis but IFNγ induced STAT3-mediated PD-L1 and MCL1 expression in EGFR-positive lung cancer cells." (PMID 34685495, 2021). "Consistently, ferroptosis inducers can inhibit growth of drug-resistant tumor, such as epidermal growth factor receptor (EGFR) inhibitor-resistant lung cancer cells." (PMID 34742351, 2021). "Chen did a retrospective study using CE-T1, T2WI, and FLAIR to predict the mutation on EGFR, ALK, and KRAS mutation in BMs from patients diagnosed primary lung cancer, verified by genotype testing." (PMID 34722274, 2021). "The emergence of drug resistance is one of the main obstacles to the treatment of lung cancer patients with EGFR inhibitors." (PMID 34356665, 2021). "For instance, different mutations in the epidermal growth factor receptor (EGFR) and tyrosine kinase inhibitors (TKI), a target for osimertinib in lung cancer, resulted in an increased drug-resistance." (PMID 35582024, 2021). "Modern pharmacology has shown that Yanhusuo extracts contain 13-methyl-palmatrubine, which has antitumor activities and can inhibit the proliferation of lung cancer A549 cells by blocking the activation of the EGFR and MAPK signaling pathways." (PMID 33868436, 2021). "Some studies have shown that the activation of MET signaling drove the resistance to EGFR inhibitors in lung cancer." (PMID 34761497, 2021).
lung cancer (continued). "The notion has been supported by previous reports that tyrosine 1068, 1086, and 1143 of EGFR played a dominant role on EGFR activation in lung cancer." (PMID 34367939, 2021). "This study provided the largest series of MET analysis data in patients with lung cancer who developed resistance after EGFR-TKI therapy." (PMID 34205733, 2021). "Hence, considering that a pilot study has found a possible relationship between depression and EGFR mutation status in patients with non–small-cell lung cancer, the EGFR intronic variant rs6970262 could be useful to characterize depressed patients with high risk to develop AD." (PMID 34956307, 2021). "The EGFR-initiated signaling cascades represent the most important pathways for lung cancer in East Asia." (PMID 33953186, 2021). "Existing evidence showed that EGFR activation upregulates PD-L1 in lung cancer, that, in turn, induces the apoptosis of T cells." (PMID 34571894, 2021). "In the present study, we will determine the role of PHLPP in EGFR TKI resistance lung cancer after EGFR-TKI therapy in vitro and in vivo." (PMID 34168988, 2021). "Recent studies showed prolonged survival for advanced epidermal growth factor receptor (EGFR)‐mutant non‐small cell lung cancer (NSCLC) patients treated with both monotherapies and combined therapies." (PMID 33626238, 2021). "Recent studies indicate co-dependence signaling by SHOC2 signaling in either KRAS mutant or EGFR mutant lung cancer cells." (PMID 34102455, 2021). "Oncogenic alterations of epidermal growth factor receptor (EGFR) signaling are frequently noted in non‐small cell lung cancer (NSCLC)." (PMID 33314735, 2021). "TATTON was initially designed as a phase Ib trial to assess the safety and tolerability of osimertinib in combination with selumetinib, savolitinib, or durvalumab for EGFR-mutant lung cancer patients." (PMID 33402199, 2021). "With the continuous development of tumor cytology and molecular biology, the potential of EGFR as a targeted therapy for lung cancer has been shown." (PMID 35082668, 2021). "Resistance to epidermal growth factor receptor tyrosine kinase inhibitors (EGFR TKIs) is a major obstacle in managing lung cancer." (PMID 34068421, 2021). "A massive number of lncRNAs have been identified to regulate the sensitivity of lung cancer cells to EGFR‐TKIs." (PMID 33931980, 2021). "For us, the IdyllaTM system or another rapid system of EGFR mutation detection is essential for reducing the timeframe of EGFR genotyping and initiating therapy in patients with lung cancer." (PMID 34898548, 2021). "In breast cancer, the growth factors TGFβ and IGF play a particularly important role in the activation of AKT, whereas primarily EGFR was shown to promote AKT activation in bone metastases of lung cancer." (PMID 34064589, 2021). "Tyrosine kinase inhibitors (TKIs) targeting EGFR-mutant lung cancers promote a range of tumor regression responses to yield variable residual disease, a likely incubator for acquired resistance." (PMID 34001994, 2021). "An increase of total sialylation of EGFR has been shown to reduce invasive properties of lung cancer cells A549, while sialidase treatment led to enhanced EGFR-mediated invasion and EGFR phosphorylation." (PMID 34069424, 2021). "Other sites include pY62/63 of the tyrosine phosphatase Shp2; Shp2 knockdown has been reported to increase cellular sensitivity to gefitinib in EGFR-TKI-resistant lung cancer cells." (PMID 33953186, 2021). "Researchers found lidocaine increased expression of miR-539 (an EGFR suppressor) in lung cancer cells treated in vitro resulting in EGFR inhibition and reduced viability, migration and invasion as well as apoptosis." (PMID 34408981, 2021). "Consistent with this idea, mutant RIT1 can transform NIH3T3 fibroblasts and confer resistance to EGFR inhibition in EGFR-mutant lung cancer cells." (PMID 34373451, 2021).